IL1B (interleukin 1 beta)
Diseases named in the same sentence as IL1B in open-access papers (continued):
Sharing a sentence is not in itself a finding about the gene and the disease.
pancreatic disease (3 papers, 2022 to 2025). "High levels of IL-1RA inhibit the signaling of IL-1β by competitively binding to IL-1 receptor, which reduce the risk of developing pancreatic disease, like via B cell-related immune pathways and slower cancer cell growth and migration." (PMID 37781392, 2023). "Research on pancreatic diseases has shown that NOX inhibitors reduced LPS-stimulated NF-κB P65 phosphorylation and IL-1β secretion in pancreatic stellate cells, thereby inhibiting pancreatic fibrosis." (PMID 41012715, 2025). "Several key factors support the improvement of pancreatic disease by Uro A. At first, Uro A inhibited ER stress and the TXNIP/NLRP3/IL-1β inflammation signal in β cells by modulating autophagy." (PMID 35745279, 2022).
parasite (3 papers, 2015 to 2021). "This included the deregulation of the IL-1β release due to parasite infections upon usage of known IL-1β inducers like LPS, IFN-γ or nigericin." (PMID 26114647, 2015). "ELISA data demonstrated that WT parasite infection could induce some IL-1β secretion upon infection and that Δmag1 parasites increased the level of IL-1β compared with WT parasites." (PMID 34006649, 2021). "THP-1 cells that lacked caspase-1 or NLRP3 were severely defective in IL-1β production in the parasite infections." (PMID 30301855, 2018).
paroxysmal AF (3 papers, 2020 to 2023). "The levels of IL-1β were similar among patients with CKD with paroxysmal AF or persistent AF." (PMID 37581942, 2023).
periventricular leukomalacia (3 papers, 2012 to 2017). Periventricular leukomalacia (PVL) is a brain injury disorder characterized by the death of the white matter of the brain due to softening of the brain tissue. "The involvement of astrocytes in the pathogenesis of WMI is suggested by increased cytokine expression (IL-1β, IL-6, and TNF-α) in both the diffuse and focal components of periventricular leukomalacia (PVL)." (PMID 22530124, 2012). "Increased levels of Il-1β were observed in amniotic fluid and/or cord blood of infants with perinatal brain injury including IVH and periventricular leukomalacia (PVL)." (PMID 28664278, 2017). "Increased levels of IL-1β are observed in the amniotic fluid and/or cord blood of infants with IVH or periventricular leukomalacia (PVL)." (PMID 27541865, 2016).
pleurisy (3 papers, 2019 to 2021). Inflammation of the pleura. "Another study documented that methanolic extract Sideritis bilgeriana suppressed TNF-α, IL-1β and leukocyte migration in carrageenan-induced pleurisy model, which is due to the presence of f phenolic and flavonoids content." (PMID 34684831, 2021).
Pneumocystis infection (3 papers, 2010 to 2024). "The expression of IL-1β was up-regulated 8.65 fold by dexamethasone and further up-regulated 2.26 fold by Pneumocystis infection." (PMID 20377877, 2010). "Among the genes that were affected by dexamethasone and further affected by Pneumocystis infection, Mgst1 and Hspa1b genes were down-regulated, while Cd14, Irf8, Il1b, Cxcl13, Cxcr4, Fn1, Irf1, Cd74, S100a9, and Spp1 genes were up-regulated in all four groups." (PMID 20377877, 2010). "Il1β mRNA levels were markedly higher compared to the other experimental groups, indicating a synergistic increase associated with the induction of COPD and Pneumocystis infection." (PMID 38542124, 2024).
polyp (3 papers, 2015 to 2025). A usually exophytic mass attached to the underlying tissue by a broad base or a thin stalk. "Our results showed that, compared to that in normal mucosal tissues, the ratio of positively stained areas for NLRP3, ASC, and IL-1β increased in polyp tissues." (PMID 40520898, 2025). "Nasal polyp tissues were cultured in the presence of 20 ng/mL IL-1β for 0 h, 10 h, 20 h and 30 h respectively." (PMID 25632272, 2015). "IL1B, IL8 and PTGS2 were significantly higher in stool from cancer patients compared to the polyp and control group (p < 0.05)." (PMID 39523395, 2024).
Polypoidal choroidal vasculopathy (3 papers, 2015 to 2022). The presence of aneurysmal 'polypoidal' lesions in the choroidal vasculature. "The results show that pro‐IL‐1β levels in nAMD, polypoidal choroidal vasculopathy (PCV), and Eales’ disease vitreous samples were significantly elevated, and IL‐1β expression in nAMD, PCV, Eales’ disease, and RVO vitreous samples was significantly elevated when compared with the control group." (PMID 30224384, 2018). "Previous studies reported that both the ~31 kDa inactive pro-form and the cleaved ~17 kDa active form of IL-1β protein were significantly elevated in the vitreous samples obtained from patients with neovascular AMD and polypoidal choroidal vasculopathy, compared to controls." (PMID 35576057, 2022).
Pseudomonas infection (3 papers, 2014 to 2021). Infections with bacteria of the genus pseudomonas. "A previous study using a chronic model of Pseudomonas infection of the lung in rats had shown that L-arginine given in drinking water resulted in lower IL-1β concentrations in BAL fluid in the L-arginine treated compared to the untreated group, whereas VEGF was increased." (PMID 24595185, 2014). "Acute Pseudomonas infection drives inflammatory cytokines such as TNF and IL-1β." (PMID 34237078, 2021). "For Pseudomonas infection settings, sham-treated mice expressed detectable TNF, but not IL-1β, in lungs." (PMID 34237078, 2021).
radiculitis (3 papers, 2018 to 2025). An inflammatory process affecting a nerve root. "Intrathecal injection of low-concentration O3 (10, 20, or 30 μg/mL) reduces the overexpression of TNF-ɑ, IL–6, and IL-1β and also significantly alleviates mechanical allodynia in chronic radiculitis rats." (PMID 30651902, 2018). "Intrathecal administration of 10 μg/mL, 20 μg/mL, or 30 μg/mL oxygen/ozone significantly attenuated the decreased mechanical PWTs, downregulated the overexpression of spinal TNF-α, IL-1β, and IL-6, and increased the expression of cGMP and cAMP in chronic radiculitis rats." (PMID 30651902, 2018). "We speculate that intrathecal administration of low-concentration O3 diminishes radicular inflammation by reducing TNF-α, IL-1β, and IL-6 in radiculitis rats." (PMID 30651902, 2018). "One study evaluated the intrathecal administration of low-dose ozone (10–30 μg/mL) in a model of chronic radiculitis, which led to a significant reduction in proinflammatory cytokines, such as TNF-α, IL-6, and IL-1β, and improved mechanical allodynia." (PMID 39598204, 2024).
renovascular hypertensive (3 papers, 2017 to 2021). "In the present study, we observed that renovascular hypertension increased the concentrations of IL-1β, IL-6, and TNF-α in the duodenum of 2K1C rats." (PMID 34777003, 2021). "Renovascular hypertension indicated an inflammatory process in the gastrointestinal tract, with increased levels of IL-1β and IL-6 and TNF-α in the duodenum." (PMID 34777003, 2021).
Respiratory distress (3 papers, 2023 to 2025). Respiratory distress is objectively observable as the physical or emotional consequences from the experience of dyspnea. "Furthermore, higher plasma levels of IL-6, IL-1β, IL-8, CCL2, (among other markers such as TNF-α) and IL-6 were also associated with post-TBI mortality, whereas higher levels of IL-6 and IL-8 were associated with respiratory distress in TBI patients." (PMID 37415924, 2023).
rhabdomyosarcoma (3 papers, 2014 to 2023). A rare aggressive malignant mesenchymal neoplasm arising from skeletal muscle. "The results of immunofluorescence and Western blotting showed that Quercetin significantly reduced the expression levels of VP1, TNF-α, and IL-1β in EV71-infected human rhabdomyosarcoma cells." (PMID 37795035, 2023). "We observed that LC3-II can still be efficiently turned over in autolysosomes of IL-1β and IFN-γ stimulated rhabdomyosarcoma cells, whilst APP turnover was incomplete and led to β-amyloid accumulation." (PMID 28167851, 2017). "This was visualized by the lipidated LC3-II turnover in IL-1β and IFN-γ treated rhabdomyosarcoma cells." (PMID 28167851, 2017).
Right ventricular hypertrophy (3 papers, 2014 to 2024). In this case the right ventricle is more muscular than normal, causing a characteristic boot-shaped (coeur-en-sabot) appearance as seen on anterior- posterior chest x-rays. "This study revealed a notable increase in the level of the oxidative stress biomarker MDA, increased expression of Nox2, a source of ROS, a decrease in pro-IL-1β levels, and the presence of right ventricular hypertrophy in rats exposed to chronic intermittent hypobaric hypoxia (CIHH)." (PMID 39456521, 2024).
scrub typhus (3 papers, 2012 to 2019). Scrub typhus is a rare dust mite-borne infectious disease caused by the Orientia tsutsugamushi bacterium and characterized clinically by an eruptive fever which is potentially serious. "Proinflammatory cytokines, such as TNF-α, IL-1β and interleukin-6 (IL-6), increase markedly in patients with scrub typhus, and attribute to the high fever occurring in most scrub typhus patients." (PMID 22723924, 2012). "The low levels of TNF-α and IL-1β observed upon admission appear to be consistent with a previous study in Vietnam, where TNF-α and IL-1β levels in scrub typhus patients were undetectable in 90% and 75%, respectively." (PMID 22192733, 2012). "In patients with scrub typhus, the levels of all cytokines measured were significantly raised as compared with healthy controls, whereas in patients with murine typhus, the levels of all except IL-1β were raised." (PMID 22192733, 2012).
secretory otitis media (3 papers, 2021 to 2024). "Spearman correlation analysis between levels of caspase-1, IL-1β, and IL-18 in the middle ear effusion and the duration of otitis media with effusion." (PMID 34805037, 2021). "Moreover, studies of Swedish children with acute or secretory otitis media have shown higher levels of IL-1β and CXCL8 in middle ear fluids if culturable, living bacteria were present, as compared with children without culturable bacteria." (PMID 38271409, 2024). "It has recently been shown, in secretory otitis media (SOM), that different inflammatory mediators, such as CXCL1, IL-16, IL-8, IL-17, IL-1β, CXCL10, and CXCL9, were found in high concentrations in middle ear fluids, in association with the presence of bacterial and viral nucleic acid levels." (PMID 38541021, 2024).
tenosynovitis (3 papers, 2014 to 2025). Inflammation of the synovial lining of a tendon sheath. "In contrast, IL13 was significantly increased and there was a tendency towards increased expression of IL1β (P = 0.055) in the ganglionitis subgroup in the older (>110 days) BB-DP animals." (PMID 25354336, 2014). "Leukocyte-rich PRP, used in some null studies, may increase pro-inflammatory cytokines (e.g., IL-1β, MMP-9), potentially exacerbating synovial inflammation in tenosynovitis." (PMID 41327174, 2025).
Thromboembolism (3 papers, 2021 to 2023). The formation of a blood clot inside a blood vessel that subsequently travels through the blood stream from the site where it formed to another location in the body, generally leading to vascular occlusion at the distant site. "However, SARS CoV-2 infection may predispose to thromboembolism 34, in which elevated levels of proinflammatory factors (including IL-6, GM-CSF, IL1B, and IFN-γ) may play a role 35-38." (PMID 33613111, 2021). "Our objective was to see if serum interleukins 1 beta (IL-1β) and soluble platelets selectin (sP-selectin) could serve as novel markers of thromboembolism in COVID-19 patients." (PMID 36522776, 2022).
Tics (3 papers, 2020 to 2023). Repeated, individually recognizable, intermittent movements or movement fragments that are almost always briefly suppressible and are usually associated with awareness of an urge to perform the movement. "The exact pathway by which IL-1β may affect in tic disorder is also not well known, and past literature on the association between tic disorder and IL-1β show mixed results." (PMID 37907857, 2023). "Additionally, although not directly about tic disorders, some studies found that OCD patients, which is comorbid with tic disorder, have increased monocytes compared to healthy controls, which in turn release more cytokines including GM-CSF, IL-1β, IL-6, IL-8, and TNF-α." (PMID 37907857, 2023).
transient cerebral ischemia (3 papers, 2012 to 2021). "At 24 h after transient cerebral ischemia (2 h ischemia/reperfusion), JQ1-treated rats exhibit a marked reduction in neurological deficits, infarct volume, and expression of pro-inflammatory mediators IL-1β, IL-6, IL-17, and TNF-α in the ischemic brain." (PMID 34604312, 2021). "After transient cerebral ischemia injury (1 h ischemia and 3 days of reperfusion), JQ1 significantly reduces infarct volume, neurological deficit score, and glial activation in ischemic mice, along with significantly decreased levels of pro-inflammatory factors IL-1β, IL-6, IL-18, and TNF-α." (PMID 34604312, 2021).
trigeminal neuralgia (3 papers, 2016 to 2025). Trigeminal neuralgia is a nerve disorder that causes a stabbing or electric-shock-like pain in parts of the face. "In a trigeminal neuralgia model established by trigeminal nerve root compression, BoNT/A administration reduced levels of inflammatory cytokines in TG, specifically IL-1β, IL-6, and TNF-α." (PMID 41441603, 2025). "Thus, targeting the CXCL13/CXCR5/ERK/TNF-α and IL-1β pathway in the TG may provide a novel therapeutic approach for the treatment of the trigeminal neuralgia." (PMID 27401148, 2016). "Similarly, in a lysophosphatidic acid (LPA)-induced trigeminal neuralgia model, a subcutaneous injection of BoNT/A into the whisker pad downregulated the expression of NLRP3, and well-known inflammatory cytokines IL-1β, IL-18, and tumor necrosis factor (TNF)-α." (PMID 41441603, 2025). "In the present study patients with trigeminal neuralgia showed lower levels of growth factor levels such as Ang-2, bFGF, HGF, SCF, TGF-α, and VEGF and higher cytokine levels of IL-1β, TNF-α, CCL2, IL-17A, IL-6, and CXCL8 in comparison with normal individuals." (PMID 34067581, 2021).
tuberculous pleurisy (3 papers, 2009 to 2016). "Our results are consistent with the previously noted association between IL-1β +3953 and tuberculous pleurisy, and VDR Fok1 and several forms of extrapulmonary tuberculosis--both noted among in Gujarati Asians living in London." (PMID 20196868, 2010). "IL-1β, IL-2, IL-6, TNF-α, PAI-1, and t-PA levels in pleural fluids of 40 patients with tuberculous pleurisy and 38 patients with tuberculous empyema were measured." (PMID 27034588, 2016).
type 1 Gaucher disease (3 papers, 2016 to 2020). "Consistent with our results, macrophages derived from peripheral monocytes from patients with type 1 Gaucher disease with genotype N370S/N370S showed an increased secretion of interleukins IL-1β and IL-6." (PMID 28166796, 2017). "Studying macrophages derived from peripheral monocytes from patients with type 1 Gaucher disease with genotype N370S/N370S, we confirmed an increased secretion of interleukins IL‐1β and IL‐6." (PMID 26486234, 2016).
ureaplasma infection (3 papers, 2012 to 2024). "With infection-related preterm labor resulting from a production of pro-inflammatory mediators, increased levels of TNF-α, IL-1β, and IL-8 may link intrauterine Ureaplasma infection with preterm birth." (PMID 29234642, 2017). "Others have demonstrated that intra-amniotic ureaplasma infection did not result in increased levels of any tested cytokines (IL-1β, IL-1 receptor antagonist, IL-4, IL-6 and TNF-α)." (PMID 22253806, 2012). "Stimulating TNF-α, IL-1β and IL-8 expression, without inducing anti-inflammatory IL-10 and IL-1ra, Ureaplasma infection might push monocyte cytokine responses toward pro-inflammation." (PMID 29234642, 2017).
uterine fibroids (3 papers, 2023 to 2025). "They did report significantly increased IL-1β/6/10 levels in the endometrium of uterine fibroids that indirect may result in increased cell proliferation and angiogenesis due to increased inflammation." (PMID 37108180, 2023).
ventilator-associated pneumonia (3 papers, 2020 to 2024). Serious INFLAMMATION of the LUNG in patients who required the use of PULMONARY VENTILATOR. "Low concentrations of IL-1β and IL-8 in bronchoalveolar lavage fluid have been validated as effective markers for exclusion of ventilator-associated pneumonia." (PMID 31810865, 2020). "Among protein-based biomarkers, only a combination of low IL-1β and IL-8 concentrations in bronchoalveolar lavage fluid has been validated in a multicentre setting in suspected ventilator-associated pneumonia." (PMID 31810865, 2020). "The VAPrapid2 trial aimed to determine whether measurement of bronchoalveolar lavage fluid IL-1β and IL-8 could effectively and safely improve antibiotic stewardship in patients with clinically suspected ventilator-associated pneumonia." (PMID 31810865, 2020). "In a ventilator-associated pneumonia mouse model caused by Acinetobacter baumannii, AZM (10 or 100 mg/kg) reduced the neutrophil influx and the release of IL-1β, IL-6, and CXCL2 in BALF." (PMID 35972289, 2022). "The VAPrapid2 trial aimed to determine whether measurement of bronchoalveolar lavage fluid IL-1β and IL-8 could improve antibiotic stewardship without compromising patient safety in suspected ventilator-associated pneumonia." (PMID 31810865, 2020).
viral meningitis (3 papers, 2020 to 2023). Inflammation of the membranes surrounding the brain and spinal cord due to a viral infection. "Previous studies have found increased levels of inflammatory cytokines and chemokines in the CSF of patients with viral meningitis, such as IL‐6, IL‐1b, TNF‐α, IL‐10, CXC family chemokines and growth factors." (PMID 37904697, 2023).
xerostomia (3 papers, 2022 to 2026). Dryness of the mouth resulting from reduced salivary secretion. "Among the inflammatory cytokines assessed - IL-6, TNF-α, IFN-γ, IL-10, IL-12p70, IL-1β, IL-8, IL-13, IL-2, IL-5, IL-7 and IL-17A, xerostomia correlated with lower levels of saliva IL-2 and TNF-α, and elevated levels of serum IL-12p70 and IL-10 (p < 0.05)." (PMID 36846089, 2023).
acromegaly (2 papers, 2020). Acromegaly is an acquired disorder related to excessive production of growth hormone (GH) and characterized by progressive somatic disfigurement (mainly involving the face and extremities) and systemic manifestations. "In patients with active acromegaly, higher production of IL-1β compared to controlled patients was observed, next to higher production of IL-1Ra compared to controls." (PMID 32458292, 2020).
alcoholic cirrhosis (2 papers, 2015 to 2020). "IL-12, IL-6 and TNF-α levels were higher in alcoholic cirrhosis (p < 0.05 for all), while IL-1β and IL-10 levels were comparable between patients with alcoholic or HCV cirrhosis." (PMID 26343741, 2015). "Single-nucleotide polymorphisms in IL-1β (−511C/T), IL-10 (−592C/A), TNF-α (−308G/A, −238G/A), TGF-β1 (−509C/T) and CTLA4 (+49A/G) were assessed in a South Indian population of 181 patients with alcoholic cirrhosis and 110 controls." (PMID 26343741, 2015).
amenorrhea (2 papers, 2022 to 2024). The absence of menses in a woman who has achieved reproductive age. "Because patients with AN often experience amenorrhoea, a difference in IL-1β levels relative to the HC group can also occur owing to an increase in these levels in the HC group post ovulation." (PMID 38892530, 2024). "Another aspect might be evidence that shows higher IL-1β levels after ovulation, as most of our patients had amenorrhea in contrast to the HC." (PMID 36061277, 2022).
Anisakis infection (2 papers, 2019 to 2025). "IL6 and IL1β are pivotal cytokines in acute inflammation, and their overexpression aligns with clinical symptoms of anisakiasis, such as abdominal pain and systemic allergic reactions." (PMID 40552294, 2025).